PRR11 (proline rich 11)
Diseases named in the same sentence as PRR11 in open-access papers (continued):
Sharing a sentence is not in itself a finding about the gene and the disease.
tumor (continued). "However, although there is growing evidence that PRR11 is an influential tumor-related gene, the link between PRR11 and Moroccan women with CC remains questionable." (PMID 39583185, 2025). "In addition, we performed experimental validation in the tumor tissues of patients, and RT‐PCR outcomes showed that PRR11 expression was upregulated in 17 of 19 patients." (PMID 40062654, 2025). "In vitro, PRR11 promoted tumor cell proliferation; in vivo, it promoted subcutaneous tumor growth." (PMID 40062654, 2025). "Moreover, these co-expressed genes were highly concentrated in the cell cycle, DNA repair and replication, cancer-related microRNA, ErbB signaling pathway, and other tumor-related biological pathways, consistent with the known function of PRR11." (PMID 36739300, 2023). "In addition, the expression of PRR11 in BLCA is significantly related to tumor immune infiltration, which will inevitably have a profound effect on the prognosis of BLCA." (PMID 36739300, 2023). "In addition, we used the ROC curve to analyze the potential effectiveness of distinguishing BLCA from non-tumor tissues by PRR11 expression." (PMID 36739300, 2023). "In considering clinical characteristics of patients with various solid tumors, PRR11 is more or less significantly correlated with greater tumor size, higher Ki-67, advanced clinical stage, more lymph node metastasis, more tumor differentiation and higher recurrence." (PMID 36551227, 2022). "In addition, an in vivo subcutaneous tumorigenicity assay also found that PRR11 knockdown diminished the tumor size and Ki-67 expression in TSCC tissues." (PMID 36551227, 2022). "Here, we demonstrated that PRR11 functions as a tumor-promoting factor in ccRCC." (PMID 34499617, 2021). "PRR11 may have been a potential target for the treatment of ccRCC in the clinic treatment and may have promoted tumor development by affecting the stability of E2F1." (PMID 34499617, 2021). "Out of the 49 tumor samples, 28 (57.1% of the patients) showed a positive expression of PRR11." (PMID 33276775, 2020). "Further, cells subjected to PRR11 knockdown exhibited a decrease in tumor growth in vivo." (PMID 33276775, 2020). "In total, 57.1% of the primary OC tumor tissue evaluated demonstrated overexpression of PRR11." (PMID 33276775, 2020). "GTSE1 and PRR11 have been reported in various types of tumor." (PMID 32180800, 2020). "Moreover, we found that genes related with cell proliferation, cell adhesion, cell motion, cell motility, and cell migration were significantly altered following PRR11 knockdown, implicating a critical role of PRR11 in tumor progression." (PMID 25971332, 2015). "Furthermore, PRR11 overexpression was found to correlate significantly with clinicopathologic features such as tumor invasion, tumor differentiation, and disease stage." (PMID 26252227, 2015). "Differential expression of PRR11 was observed between tumor and normal tissue at various sites." (PMID 25971332, 2015). "Since silencing PRR11 lead to marked inhibition of tumor cell growth and increased survival, the transcriptional effects of PRR11 expression was probed using cDNA array, specifically by comparing the gene expression patterns between PRR11-KO and wild-type cells." (PMID 25971332, 2015). "High PRR11 expression may increase the risk of transformation from non‐muscle‐invasive bladder cancer (NMIBC) to muscle‐invasive bladder cancer (MIBC), further driving the invasive and metastatic behavior of the tumor." (PMID 40062654, 2025). "Thus, we predict that targeting PRR11 could effectively reduce the number of tumor cells by blocking S‐phase progression, demonstrating its profound potency in tumor therapy." (PMID 40062654, 2025). "Therefore, we hypothesize that PRR11 indirectly affects the negative regulation of the tumor immune microenvironment and influences the phenotype of BLCA by regulating immune cell infiltration." (PMID 36739300, 2023).
tumor (continued). "In particular, it should be pointed out that these main roles in regulating tumor immune microenvironment, such as marker sets related to M2 macrophage, tumor-associated macrophages (TAM), Treg and T cell exhaustion, displayed a strong and significant positive correlation with PRR11." (PMID 36739300, 2023). "Therefore, we suggest that PRR11 in BLCA tends to induce a tumor-suppressive immune microenvironment, and the up-regulation of its expression may directly or indirectly alter the type and level of immune cell infiltration." (PMID 36739300, 2023). "In addition, PRR11 obviously promoted xenograft tumor growth in vivo." (PMID 36551227, 2022). "Moreover, in vivo tumorigenicity was suppressed by PRR11 in tumor volume and weight." (PMID 36551227, 2022). "Moreover, the staining intensity of the PRR11 protein gradually increased along with the progression of OC, from low expression in benign tumors to intensive positivity in tumor emboli indicating that PRR11 might be used as an OC tumor biomarker." (PMID 33276775, 2020). "Overexpression of PRR11 in HC tumor cells may predict a more aggressive clinical behavior." (PMID 25971332, 2015). "Therefore, we postulated that PRR11 might promote tumor growth by affecting the cell cycle." (PMID 40062654, 2025). "IHC score indicated that PRR11, KIF11, RACGAP1, YY1, CREB1 expression was significantly increased in HCC tissues compared to adjacent para-tumor tissues." (PMID 39530087, 2024). "An examination of tumor specimens revealed an escalation in the expression of KIF18A, in conjunction with heightened levels of CENPE, SNHG4, KIAA1841, CDCA2, and PRR11 mRNA." (PMID 38495502, 2024). "The mRNA expression levels of STMN1, CLSPN, MDK, RNFT2, PRR11, and RNF157 were significantly increased in HCC tumor tissue; on the contrary, GHR was significantly decreased compared with normal tissues." (PMID 37542549, 2023). "Exploration of its biological activities showed that PRR11 silencing suppressed the proliferation, invasion and migration of CRC cells and xenograft tumor growth in vivo." (PMID 36551227, 2022). "Relatively higher expression levels of PRR11 are also detected in 12 ESCC cell lines and 38 ESCC tissues than in 2 normal esophageal epithelial cells (NEECs) and the matched adjacent non-tumor tissues." (PMID 36551227, 2022). "In 216 GC patients, PRR11 expression is positively correlated with TNM stage and tumor differentiation, accompanied by the shorter overall survival of these patients." (PMID 36551227, 2022). "Co-expression of PRR11, UCHL1, EGR1, and SNAT1 was found to be a frequent event in HC tumor samples, indicating a cross-talk among these four proteins." (PMID 25971332, 2015). "Univariate COX regression analyses demonstrated that tumor size, tumor stage, lymph nodes positivity, TNM stage, tumor differentiation and PRR11 expression were significantly correlated with a decreased overall survival." (PMID 26252227, 2015). "In addition, there was a significant correlation between PRR11 expression and TMB and tumor immune infiltration." (PMID 36739300, 2023). "The calculation results demonstrated that in the two datasets of TCGA-BLCA and GSE48276, PRR11 and Immunescore had a significant negative correlation, and a significant positive correlation with tumor purity." (PMID 36739300, 2023). "Further exploration on clinical characteristics of 80 pairs of HCC tissues and adjacent non-tumor liver tissues confirmed that PRR11 overexpression contributes to larger tumor size, improved TNM stage and shorter overall survival." (PMID 36551227, 2022). "PRR11 has been widely reported in many tumor types, but its biological function has not been studied in depth." (PMID 34499617, 2021). "Proline rich 11 (PRR11), a novel tumor-related gene, has been identified in different tumors." (PMID 34499617, 2021). "Additionally, recent studies have shown that proline-rich protein 11 (PRR11), which is also involved in cell cycle regulation, is related to tumor malignancy." (PMID 27613831, 2016).
tumor (continued). "Western blotting and RT-PCR assay further confirmed that PRR11 protein and mRNA was increased in tumor samples compared with that in the noncancerous tissues." (PMID 26252227, 2015). "Of these tumor samples, 107 out of 216 (49.5%) had positive PRR11 expression and 109 cases showed PRR11 negative expression." (PMID 26252227, 2015). "In prior studies, PRR11 was suggested to be a negative effector in cell cycle regulation of tumor cells." (PMID 25971332, 2015). "Based on this, we believe that PRR11 may increase the level of CD8+ T cell infiltration in BLCA tumor tissues to a certain extent, but these tumor-infiltrating CD8 + T cells cannot exert their ability of tumor suppressor due to T cell exhaustion and the suppressive immune microenvironment." (PMID 36739300, 2023). "In addition, the potential of PRR11 to initiate tumor cell proliferation and migration in ccRCC depends on the novel function of the classic transcription factor E2F1." (PMID 34499617, 2021). "In addition, PRR11 expression was significantly positively correlated with tumor stage and pathological grade, and although FBXW7 expression did not significantly differ with tumor stage or tumor size, it exhibited a negative correlation trend." (PMID 40083925, 2025).
cancer (22 papers, 2012 to 2025). A tumor composed of atypical neoplastic, often pleomorphic cells that invade other tissues. "PRR11 is a gene that plays a significant role in cell cycle progression and is often implicated in cancer progression, whilst it is associated with poor prognosis in a number of cancers." (PMID 40871563, 2025). "PRR11 was identified as a key smoking-associated gene that influences the efficacy of immune checkpoint therapy by modulating the stemness of these cancers." (PMID 38760964, 2024). "The proline-rich protein 11 (PRR11) is a newly identified oncogene associated with a poor prognosis in several human cancers." (PMID 33276775, 2020). "For example, PRR11 (proline rich 11), mutations in which have been associated with cancer, was shown to regulate S to G2-M phase transition." (PMID 30452682, 2019). "We previously identified proline-rich protein 11 (PRR11) as a novel cancer-related gene that is implicated in the regulation of cell cycle and tumorigenesis." (PMID 28257042, 2017). "This approach revealed that PRR11 was overexpressed in 28 cancer types, with expression downregulated only in LAML." (PMID 40062654, 2025). "This study aimed to identify smoking-related differential genes in NSCLC and BLCA, analyse their roles in patient prognosis and immune checkpoint therapy through subgroup analyses, and shed light on PRR11 as a crucial prognostic gene in both cancers." (PMID 38760964, 2024). "We initially used the Oncomine database to analyze the expression differences of PRR11 mRNA between cancer and normal tissues." (PMID 36739300, 2023). "The results of KEGG pathway enrichment analysis demonstrated that PRR11 co-expressed genes were mainly involved in the cell cycle, homologous recombination, microRNAs in cancer, RNA transport, DNA replication, and ErbB signaling pathway." (PMID 36739300, 2023). "Conversely, our reviewed results focus on a limited number of human cancers, appealing to the reliable evaluation for PRR11 expression in other tumors." (PMID 36551227, 2022). "Based on these investigational results, targeted therapies of PRR11, especially interactions between PRR11 and miRNAs, lncRNAs and other molecules, would be utilized for cancer treatment." (PMID 36551227, 2022). "Though PRR11 expression is downregulated in LAML patients from the GEO database, the oncogenic role of PRR11 in a variety of human cancers have already been verified." (PMID 36551227, 2022). "Intriguingly, PRR11 expression is significantly upregulated in various human cancers, except acute myeloid leukemia (LAML), per the gene expression omnibus (GEO) database." (PMID 36551227, 2022). "In particular, PRR11 also serves as a promising prognostic indicator in a limited number of human cancers, gradually manifesting its potential application for targeted therapies." (PMID 36551227, 2022). "Aiming at cancer stem cells (CSCs), PRR11 knockdown reduced CSC-like phenotypes and tumorigenicity of ESCC cells in vitro and in vivo through Wnt/β-catenin signaling." (PMID 36551227, 2022). "PRR11 has been found highly expressed in various cancer types and strongly correlated with their poor outcome." (PMID 36060253, 2022). "In order to thoroughly explore the cancer-promoting effects of PRR11, we integrated and analyzed the RNA-seq generated by ourselves and the TCGA pan-cancer data." (PMID 36060253, 2022). "Several studies have indicated that PRR11 is overexpressed in various cancers, including lung, ovarian, esophageal and pancreatic cancers." (PMID 34488538, 2021). "PRR11 is highly expressed in malignant tumors such as pancreatic cancer 5, hilar cholangiocarcinoma 6, and ovarian cancer." (PMID 34659555, 2021).
cancer (continued). "Results showed that knocking down the expression of PRR11 significantly blocked the growth of cancer cells (HO8910 and SKOV3) both in short-term proliferation and long-term proliferation assays." (PMID 33276775, 2020). "RNA-seq analysis of the treated tumors showed that among 51 genes in 17q23, PRR11 was the only gene significantly overexpressed in resistant vs. sensitive cancers (Log2 fold change = 1.15, FDR = 0.004, p = 1.02E-05)." (PMID 33127913, 2020). "Despite the increased need to unravel the molecular mechanisms and pathological features of PRR11 in the development of OC, existing studies have directed their focus to the expression of PRR11 in the pathological and clinical features of other cancer tumors." (PMID 33276775, 2020). "Aberrant activation of PI3K/AKT/β-catenin has been suggested as a mechanism by which PRR11 promotes cell proliferation in ovarian and hepatocellular carcinoma, but the molecular basis for a potential role of PRR11 in cancer virulence is unclear." (PMID 33127913, 2020). "The potential therapeutic value of targeting PRR11 has been validated in a variety of cancers." (PMID 40062654, 2025). "Bioinformatics analysis has revealed that PRR11 comprises a bivalent nuclear localization signal, a pair of proline-rich regions and zinc finger domains, which are involved in the transduction of cell signals and mediate a cascade of cancer-related processes." (PMID 39583185, 2025). "The TCGA and GTEx databases were used for systematic pan‐cancer expression analysis of PRR11." (PMID 40062654, 2025). "Another study revealed that PRR11 could promote cell proliferation by regulating PTTG1 through interaction with the transcription factor E2F1 in the pan-cancer setting." (PMID 38427643, 2024). "PRR11 is a relatively new potential candidate oncogene, which may play an important role in the initiation and progression of cancer." (PMID 36739300, 2023). "Our findings confirmed that downregulated PRR11 could inhibit the proliferation and migration of different cancer cells, which were consistent with previous results in the lung, pancreatic, and gastric cancer cells." (PMID 36060253, 2022). "More importantly, PRR11 also serves as a prognostic biomarker for several human cancers." (PMID 36551227, 2022). "Therefore, finding out the molecular regulation mechanisms of PRR11 upregulation in promoting tumorigenesis and development of pan-cancers will help us understand its function and develop new diagnostic and therapeutic methods." (PMID 36060253, 2022). "In this review, we try to generalize functional activities, related signaling pathways and biological molecules of PRR11 in malignancies and the potential application of PRR11 for targeted therapies, thus contributing to further exploration of PRR11 in cancer treatment." (PMID 36551227, 2022). "Furthermore, recent evidences and our results provided a strong case for PRR11 regulation in S phase of the cell cycle in many cancers." (PMID 36060253, 2022). "The relevant biological functions of PRR11 in pan-cancer development are not well understood." (PMID 36060253, 2022). "The upregulated proline rich 11 (PRR11) plays a critical role in cancer progression." (PMID 36060253, 2022). "In this study, we examined the expression pattern of PRR11 in different types of cancers with ≥ 30 normal tissues from TCGA and explored its related clinical pathological, to clarify the application prospect of PRR11 as a prognostic marker of pan-cancers." (PMID 36060253, 2022). "All these results indicated that PTTG1 showed the same trends of expression and poor outcome as PRR11 and may be an oncogene in pan-cancer." (PMID 36060253, 2022).